HK2 (hexokinase 2)
Diseases named in the same sentence as HK2 in open-access papers (continued):
Sharing a sentence is not in itself a finding about the gene and the disease.
cancer (continued). "Hexokinase 2 (HK2), preferentially expressed in cancers, is bound to the outer mitochondrial membrane (OMM), where it has privileged access to ATP generated in the mitochondria, thus facilitating phosphorylation of glucose, crucial for both OXPHOS and aerobic glycolysis." (PMID 38007466, 2023). "The normal-like samples did not stain for GLUT1, HK2, and LDHA, with the differences being significant and near-significant with regard to the LDHA and HK2 expression in the cancer sections (44.9% positivity for LDHA, p = 0.018; 35.5% positivity for HK2, p = 0.050)." (PMID 36765947, 2023). "YAP plays a vital role in its downstream targets lncRNA breast cancer antiestrogen resistance 4 (lncRNA BCRA4), which contributes to the transcription of two glycolysis activators, hexokinase 2 (HK2) and 6‐phosphofructo‐2‐kinase (PFKFB3), and then promotes the YAP‐dependent glycolysis in turn." (PMID 37576865, 2023). "Interestingly, HK2 and PFKP levels are highly expressed in cancer cells, which correlates with higher glycolysis rates." (PMID 37904253, 2023). "They regulate the expression of glycolytic enzymes including hexokinase 2 (HK2), pyruvate kinase M2 isoform (PKM2), lactate dehydrogenase A under normoxia and hypoxia, and promote the survival of cancer cells and the growth of cancer tissues." (PMID 35912204, 2022). "Besides the repression of AFP, ZHX2 also repressed the cancer biomarkers pyruvate kinase M1/2 (PKM) and hexokinase 2 (HK2) in HCC." (PMID 36232466, 2022). "While the role of HK2 in autophagy has been documented in the literature, our study here represents the first observation to link glycolysis and autophagy in the case of TNBC regarding the anti-cancer effect of lovastatin." (PMID 36186902, 2022). "Ectopic c-MYC expression could drive aerobic glycolysis in cancers via the direct upregulation of GLUT1, LDHA, HK2, and PKM2." (PMID 35571245, 2022). "We speculate that this is because HNK reduces the expression of HIF-1α protein, which in turn inhibits the transcription of key molecules GLUT1, HK2, and PDK1 on the glycolysis link, resulting in a decrease in the glycolysis level of cancer cells." (PMID 35350760, 2022). "There was an upregulation of genes participating in glucose transport, mainly GLUT6, the glycolytic enzymes HK1 and HK2, the phosphofructokinase PFKFB3, the enolases ENO3, and ENO2, and the lactate dehydrogenase LDHA, similar to the Warburg effect in cancer cells." (PMID 35163725, 2022). "Another glycolytic pathway member, Hexokinase 2(HK2), is a rate limiting enzyme involved in phosphorylation of glucose to glucose-6-phosphate and also reported to be up-regulated by HIF-1α in hypoxic cancer cells." (PMID 36014432, 2022). "PLK3 inhibits cancer cell growth and suppresses cellular glucose metabolism through the heat shock protein 90 (HSP90)/signal transducer and activator of transcription 3 (STAT3)/hexokinase 2 (HK2) pathways." (PMID 35487956, 2022). "However, it has been reported that an increased laminar flow in circulating cancer cells enhances the transcription factor ATOH8, which, in turn, induces the expression of the glycolytic enzyme HK2." (PMID 35681715, 2022). "Currently, a HK2 specific inhibitor is not available, but a glucose analog, 2-deoxy-D-glucose (2-DG) has been extensively evaluated as an agent for inducing cancer cell death and cancer therapy." (PMID 35252279, 2022). "For example, metformin can reduce mTORC1 activity in HCC cells, inhibiting protein synthesis and inducing cancer cell death in the absence of HK2 expression." (PMID 36230492, 2022). "In addition, previous studies have indicated that several proteins, including glucose transporter 1 (GLUT1), hexokinase 2 (HK2), and lactate dehydrogenase A (LDHA), in glycolysis are often overexpressed in cancer." (PMID 34575112, 2021).
cancer (continued). "Cancer cells exhibit high glycolytic activity during rapid proliferation even in the presence of normal oxygen concentrations in culture; therefore, we examined changes in doubling times following the HK1 and HK2 deletions." (PMID 34895333, 2021). "On the other hand, co‐culture with TANs led to increase of SPI1 expression and its enrichment on HK2 or PGK1 promoter in LoVo and HCT116 cells, resulting in increase of HK2 or PGK1 promoter activity and transcript levels, while silencing of SPI1 in cancer cells reduced these effects." (PMID 34841706, 2021). "Furthermore, the enzyme hexokinase 2 (HK2) converts glucose to glucose-6-phosphate in the first step of glucose metabolism and promotes the Warburg effect in cancer cells." (PMID 34445360, 2021). "In addition, forced or impaired SPI1 expression respectively enhanced or reduced the levels of HK2 and PGK1 in cancer cells." (PMID 34841706, 2021). "As the major rate-limiting enzymes in the glycolysis pathway, HK2 and PFKL overexpression promotes Warburg effect, which could assist the uncontrolled proliferation of cancer cells." (PMID 35004308, 2021). "Although total and free PSA testing is available in many clinics, antibodies for intact PSA and hK2 used in most published series were custom made, and are not available in most cancer centers." (PMID 33490732, 2021). "There was increase and decrease in SPI1 enrichment, promoter‐luciferase reporter activity, as well as levels of HK2 and PGK1 in cancer cells stably over‐expressing or silencing SPIB, which was eliminated by silencing or ectopic expression of SPI1, respectively." (PMID 34841706, 2021). "The use of the 4KLK is still limited by the lack of accessibility to intact PSA and hK2 antibodies in many cancer centers." (PMID 33490732, 2021). "HK2 and LDHA are the glycolytic pathway genes playing crucial roles in the Warburg effect in cancer cells and their inhibition by DOX and apigenin co-administration possibly hamper the growth and proliferation of cancer cells." (PMID 34715860, 2021). "Increases in the expression of several key glycolytic enzymes such as hexokinase 2 (HK2), pyruvate kinase muscle isozyme‐2 (PKM2) and lactate dehydrogenase type A (LDHA) are well‐documented in cancers exposed to hypoxic conditions." (PMID 33400855, 2021). "By using various cancer databases, HK2, but not HK1, positively correlates with HNSCC progression in a stage-dependent manner." (PMID 32195170, 2020). "It is reported that HK2 can bind with VDAC, localize in mitochondria outer membrane and maintain the integrity of mitochondrial structure, leading to the inhibition of apoptosis and promotion of aerobic glycolysis in cancer cells." (PMID 33143000, 2020). "Therefore, the inhibition of HK2, PFK, or PK to attenuate or suppress glycolysis in cancer cells is currently considered a potentially effective anti-cancer strategy." (PMID 32273843, 2020). "The interaction of HIF-1 and c-MYC directs cancer cells to glycolysis by upregulating the glucose transporter 1 (GLUT1) which increases glucose uptake, and hexokinase 2 (HK2) which catalyzes the first step of glycolysis, and PDK1 which suppresses mitochondrial respiration." (PMID 33028364, 2020). "Surprisingly, differential HK1 level could better stratify cancer-specific survival rates than HK2 in HNSCC patients, suggesting that HK1 and HK2 might play differential roles during HNSCC tumorigenesis." (PMID 32195170, 2020). "Hence, certain key proteins involved in this disruptive metabolism, such as GLUT, hexokinase-2 (HK2) and phosphoglycerate dehydrogenase (PHGDH), which are overexpressed in cancer, have been examined as possible targets." (PMID 33330106, 2020).
cancer (continued). "Lonidamine is a selective inhibitor of the soluble and mitochondrial-bound HK2 iso-enzyme, which is present in malignant cells but not in healthy cells and is effective in the treatment of diverse cancer cells." (PMID 31803611, 2019). "Thus, in rapidly proliferating cancer cells, the first phase of the UM0112176-dependent decrease in ATP levels correlates with the rapid dissociation of HK2 from mitochondria." (PMID 31558701, 2019). "The present link between HK2 and VEGF suggests that dual targeting of HK2 and VEGF in ovarian or other cancers may be a promising alternative therapeutic approach, which should be evaluated in future studies." (PMID 31212816, 2019). "Overexpressions of Glut1, HK2, and LDH-A have been found in many types of cancers, including LC." (PMID 31781603, 2019). "In contrast, silencing of HK2 did not influence cancer cell growth as analysed by both the MTT cell growth and BrdU incorporation assays, as well as in the anchorage-dependent and independent clonogenic growth assays." (PMID 29721175, 2018). "HK2 is the hexokinase isoform that is not highly expressed in most mammalian tissues but is generally induced in cancer cells by multiple mechanisms." (PMID 29687779, 2018). "Consequently, HK2 knockdown by DOX-induced shHK2 resulted in a greater reduction of both glucose consumption and lactate production more pronounced in HK1−HK2+ cancer cells (Hep3B, Huh7) compared to HK1+HK2+ cancer cells (SUM159)." (PMID 29988332, 2018). "The results revealed that most cancer types exhibit low to moderate levels of the HK1 protein but display moderate to high levels of HK2 protein (data not shown)." (PMID 29721175, 2018). "Here we provide direct evidence that HK2 is necessary and sufficient to promote metastasis in PDAC, as its increased expression promotes invasion and its knockdown inhibits cancer cell extravasation and colonization at distant organ sites, important components of the metastatic cascade." (PMID 28915575, 2017). "In summary, this study not only uncovered the critical roles of hypoxia-down-regulated miR-125a in the Warburg effect of HCC cancer but also explored the molecular mechanisms through which miR-125a regulated HCC glycolysis and progression and identified HK2 as a direct target gene." (PMID 28596599, 2017). "Several other enzymes in glycolysis are also increased in cancer cells, but unlike HK2 they are also expressed in normal cells." (PMID 29137232, 2017). "HK2 siRNA significantly suppressed the expression of HK2 protein in SW480 cancer cells compared with that of negative control." (PMID 28427443, 2017). "Finally, we revealed that the miR-125a/HK2 axis is functionally important for regulating glycolysis of HCC cell and progression of cancer in vitro and in vivo." (PMID 28596599, 2017). "As we expected, isoflurane treatments significantly up-regulated both protein and mRNA expressions of HK2 and PKM2, whose overexpression in cancer cells resulted in up-regulated aerobic glycolysis and LDHA, which catalyzes the interconversion of pyruvate and L-lactate." (PMID 28951521, 2017). "We observed HK2-CGI hypermethylation only in HK2negativeHK2-CIMP HCCs and in SNU449 cells, which might be explained by a model of de novo methylation in cancer." (PMID 27260001, 2016). "Collectively, these data support that pharmacological inhibition of HK2-mediated glycolysis in KP2 and H23 cells might reduce cancer cell growth through inducing cell cycle arrest and activating autophagy and apoptosis pathway." (PMID 26884725, 2016). "NDRG2 inhibited glucose transporter 1, and three key regulatory enzymes HK2, PKM2 and LDHA in glycolysis, NDRG2 also inhibited glutamine transporter ASCT2 and glutaminase GLS1 in glutaminolysis, along with the inhibition of c-Myc in cancer cells." (PMID 26317652, 2015). "Our search for HK2 loci in 26 patients of The Cancer Genome Atlas (TCGA) project revealed 13 loci that are not in the reference sequence." (PMID 24920817, 2014).
cancer (continued). "Overexpression of hexokinase 2 (HK2), which plays a key role in glucose metabolism and apoptosis, may also influence BrM in breast and other cancers." (PMID 22481931, 2012). "In this study, we found that HK2 and HMGCS1 inhibited the elimination of ASSs by binding to P62 to prevent reductions in the lactate and cholesterol concentrations, respectively, and nutrient supplementation provided conditions sufficient for the growth of cancer cells." (PMID 40097416, 2025). "Key enzymes in glycolysis such as glucose transporter 1 (GLUT1), hexokinase 2 (HK2), phosphoglycerate kinase 1 (PGK1), pyruvate kinase M2 (PKM2), lactate dehydrogenase A (LDHA), and monocarboxylate transporter 4 (MCT4) have been observed to be highly expressed in cancer tissues." (PMID 39594816, 2024). "During the aerobic glycolysis of cancer cells, Pyruvate dehydrogenase kinase 4 (PDK4) is one of the most important factors which can direct carbon flux into glycolysis from oxidative phosphorylation (OXPHOS) and HK2 (hexokinase 2) is a key rate-limiting enzyme in aerobic glycolysis." (PMID 38343637, 2024). "Furthermore, elevated expression and activity of key metabolic genes, including hexokinase 2 (HK2), pyruvate kinase muscle 2 (PKM2) and lactate dehydrogenase A (LDHA), have been documented in various human cancers and are correlated with poorer patient survival outcomes." (PMID 39661026, 2024). "For example, miR-143 decreases the glucose metabolic rate by inhibiting hexokinase 2 expression (HK2, which catalyzes the phosphorylation of d-glucose and d-fructose to glucose 6-phosphate and fructose 6-phosphate), and as a result, prevents the proliferation and growth of cancer cells." (PMID 37161350, 2023). "No cases of resistance to 2-DG, an HK2 inhibitor, in cancer have been reported." (PMID 36609747, 2023). "The inhibition of HK2 in cancer therapy may be doubted due to its non-specificity and systemic toxicity, as well as the fact that tumors expressing HK2 can also express HK1." (PMID 37298093, 2023). "HKs (HK1 and HK2), PFK1 and PFK2, G6PD, pyruvate kinase, phosphoglycerate dehydrogenase (PHGDH), lactate dehydrogenase, phosphoglycerate kinase 1 (PGK1), enolase (ENO), isocitrate dehydrogenase (IDH), and glucose transferase (GLUT) serve as ideal pharmacological targets to treat cancer." (PMID 36984785, 2023). "Hexokinase 2 (HK2), pyruvate kinase 2 (PKM2), and lactate dehydrogenase A (LDHA) can regulate EMR, and abnormal expression of these enzymes may promote the Warburg effect in cancer cells 5-7." (PMID 35711836, 2022). "Considering that c-Myc functioned as a key downstream effector in aberrantly activated FGFR signaling in cancer 21 and that FGF-induced vascular development was dependent on endothelial glycolysis via MYC/HK2 43, we also tested whether HK2 downregulation by FGFRi was c-Myc dependent in this study." (PMID 36168616, 2022). "While not yet defined molecularly, it is formally possible that reduced Hk2 activity may be advantageous in cancers that have not yet transitioned to a high-glycolytic state." (PMID 35235554, 2022). "We also knockdown c-Myc, which was the downstream effector of FGFR via MEK-ERK signaling in FGFR aberrant cancer 21, and no obvious HK2 expression change was exhibited in NCI-H1581 and Hep3B cells, indicating the different regulatory mechanisms by FGF/FGFR for HK2 and c-Myc." (PMID 36168616, 2022). "In addition, by stimulating hexokinase-2 (HK2) expression, HOTAIR may be engaged in the processes of cancer cell energy metabolism, including glucose uptake, lactate production, and ATP production." (PMID 35565245, 2022).
cancer (continued). "Moreover, unlike other hexokinases, GCK is not inhibited by its product (G6P) so that the reaction rate is driven by the supply in glucose but not by the demand for end products as it is the case for HK2 in cancer cells." (PMID 35055105, 2022). "In addition, knockdown of HK2 was found to inhibit cancer development in mouse models and, more importantly, did not activate HK1 expression." (PMID 36230492, 2022). "HK2 is most closely related to malignant tumors, and dioscin has been shown to promote ubiquitination and degradation of c-myc by enhancing the binding of the E3 ligase FBW7 to c-myc, which helps to inhibit HK2 and inhibit glycolysis in CRC cells to exert antitumor activity." (PMID 36778600, 2022). "This is interesting because it may indicate that inhibition of HK2 in cancer cells does not necessarily lead to its death." (PMID 35269760, 2022). "There is no data on this point; however, we note that not all cancer cells are subject to the Warburg effect, so elevated Hk2 function may not always be beneficial to cancer cells." (PMID 35235554, 2022). "Furthermore, other key enzymes and proteins mediating the Warburg effect, such as monocarboxylate transporter 1 and 4, hexokinase 2 (HK2), lactate dehydrogenase A (LDHA), and pyruvate dehydrogenase kinase 1 (PDK1), have also been reported to be overexpressed in different cancers." (PMID 36497394, 2022). "Activated AKT prevents the transport of pyruvate into the mitochondria for the TCA cycle and switches cancer metabolism from oxidative phosphorylation to aerobic glycolysis by triggering GLUTI expression, stimulating phosphofructokinase activity, phosphorylating HK2, and inhibiting PKM2 activity." (PMID 34540667, 2021). "Therefore, in this study, we explored the mitochondrial apoptosis mediated by PGC1α through the HSP70/HK2/VDAC1 signaling pathway, which may provide a new strategy for inducing apoptosis of cisplatin-resistant cancer cells." (PMID 33802591, 2021). "In addition, a potential role of HK2 in altering FN1 expression in cancer cells has not been reported." (PMID 34758823, 2021). "Beyond the critical role in glucose metabolism, HK2 can form a complex with voltage-dependent anion channel (VDAC) on the outer mitochondrial membrane to reduce the release of cytochrome c, which eventually confers therapeutic resistance and promotes cancer cells survival." (PMID 32424132, 2020). "While Sox2 might not be directly involved in the survival of differentiated cancer cells, its downstream targets like HK2 and PDK2 might be contributing in viability of the cells through their key roles in metabolic processes." (PMID 32170113, 2020). "However, unlike HK1, HK2 shows high expression to enhance glucose flux into various metabolic pathways in most cancer cells." (PMID 32083006, 2020). "Thus, HK2 expression and glycolysis could be potential biomarkers or therapeutic targets in NSCLC patients in the era of cancer immunotherapy." (PMID 31718692, 2019). "Here, we chose 25 nM HK2 siRNA or 5 mM 2-DG, a concentration resulting in around 10% cells viablility in both HCT116 and RKO cells, to evaluate whether HK2 was critical for B7-H3-regulated cancer chemoresistance." (PMID 30952834, 2019). "Notably, no change in the protein levels of HK-2, the main isoform expressed in cancer, was detected, suggesting possible post-translational modification(s) of the enzyme that were not investigated." (PMID 30367149, 2019). "Interestingly, unlike in other mouse models of cancer, HK2 deletion in the prostate of Pbsn-Cre; Ptenf/f mice is not only cytostatic but also cytotoxic." (PMID 29687779, 2018). "However, most previous studies on HK2 in cancer did not examine the contribution of HK1 to cancer glycolysis." (PMID 29988332, 2018). "Unlike HK1+HK2+ cancers, HK1−HK2+ cancers are sensitive to HK2 silencing-induced cytostasis." (PMID 29988332, 2018).